TNF (tumor necrosis factor)
Diseases named in the same sentence as TNF in open-access papers (continued):
Sharing a sentence is not in itself a finding about the gene and the disease.
tumor (continued). "Interestingly, for the 2D cell arrangement, the CMA-ES algorithm was able to find two optimal treatment strategies, that is, a set of parameters for the TNF pulse that kills every tumor cell in all three replicates." (PMID 35463947, 2022). "Importantly, VPA treatment in bone marrow-derived MDSC co-culture with T cells reactivated T cells ability for TNFα production thus conferred anti-tumor effect." (PMID 35140716, 2022). "Moreover, PTPR enhanced the killing of the tumor cells by T cells, as well as the expression levels of TNF-α and IFN-γ in T cells." (PMID 36376293, 2022). "Compared with the human immortalized normal ductal epithelial cell line, the expression of NLRP1 and TNF in tumor cell lines was remarkably higher, the expression of NLRP1 was the highest in BX cell lines, and the expression of TNF was the highest in PANC-1 cell lines." (PMID 35785176, 2022). "Moreover, the injection of TNF-α brings with it the important PMN tumor colonization, with a role in combating uncontrolled cell multiplication." (PMID 35563587, 2022). "Although TNF inhibition caused weight gain in tumor-bearing mice, the modulation of TNFα has not given any clinical benefit in different human trials." (PMID 36078078, 2022). "IFNγ and TNFα can co-induce dormancy in tumor cells to promote carcinogenesis." (PMID 35582541, 2022). "Another study predicted by network pharmacology that Baitouweng decoction may affect tumor cell proliferation, migration, apoptosis, and angiogenesis by regulating signaling pathways such as TNF, PI3K-Akt, HIF1, and vascular endothelial growth factor." (PMID 35814470, 2022). "The ability of TNF to invoke apoptosis in tumor cells is well-established." (PMID 36081549, 2022). "Tumor-associated macrophages (TAM), myeloid-derived stem cells (MDSC), and lymphocytes Th1/Tc infiltrating the TME influence the epithelial cells undergoing TME through the secretion of IL-1β, IL6, IL8, IL10, IL17, TGF-β, or TNFα." (PMID 35884974, 2022). "Among them, TNF-α was proven by some studies to accelerate tumor growth, and we then examined whether it could also enhance MB cell proliferation." (PMID 35725556, 2022). "In B16F-10 melanoma cells, andrographolide inhibits the expression of granulocyte-macrophage colony-stimulating factors and pro-inflammatory cytokines such as TNF-α, IL-1β and IL-6 genes, inhibits the activation of NF-κB and AP-1 to promote apoptosis of tumor cells." (PMID 36238575, 2022). "TPM3, CHMP4C, EEF1A1, FASN, TNF, S100A10, and IL1A represent a high-risk score and poor prognosis, suggesting that these genes may be associated with the tumor process in patients with CC and appear to be pro-oncogenes." (PMID 36685937, 2022). "In addition to endocrine disorders, immuno-inflammatory responses such as adipose tissue releases proinflammatory cytokines such as TNF-α or IL-6, which promote angiogenesis and cell proliferation leading to rapid tumor growth." (PMID 35463353, 2022). "In addition, TNF-α can also be directly cytotoxic to tumor cells by binding to TNF-R1, which is expressed on most tissues." (PMID 36066630, 2022). "However, TP/TNF-α cotreatment dramatically inhibited the tumor growth of AGS and MKN45 cells and firmly proved that TP treatment increased the sensitivity of AGS and MKN45 cells to TNF-α in vivo." (PMID 36110523, 2022). "After recognizing the damaged mtDNA, DCs up-regulate CD86, CD83, and human leukocyte antigen (HLA-DQ) expression and enhance the transcription and release of TNF-α and other inflammatory factors, thereby contributing to forming an anti-tumor inflammatory microenvironment." (PMID 35326602, 2022). "In the presence of tumor necrosis factor-alpha (TNF-α), caspase-8 is activated in tumor cells." (PMID 35883480, 2022). "TNF-α is a well-known tumor-suppressive cytokine that induces apoptosis in specific types of cells." (PMID 36140220, 2022). "In this study, TNF-α acted as a protective factor against inflammation and a tumor suppressor." (PMID 36140220, 2022).
tumor (continued). "N1 neutrophils could directly play an anti-tumor role by modulating the expression levels of cytotoxic effectors, including tumor necrosis factor-α (TNF-α), granzyme B (GZMB), and elastase (ELANE)." (PMID 35784745, 2022). "However, the inhibitors of apoptosis (IAP) are frequently overexpressed in tumour cells, protecting them from TNF-induced, RIPK1-mediated cell death." (PMID 35327375, 2022). "In addition, we showed in a previous study that infliximab, one of the inhibitory agents for TNF-α activity, was ineffective in attenuating tumor-induced osteoclastogenesis." (PMID 36614130, 2022). "We investigated if tumor-triggered MCs could transfer TNF-α into tumor cells following the formation of TnT." (PMID 35740607, 2022). "In addition, TNF signaling has been shown to act as a tumor accomplice in HNSCC by decreasing tumor cell apoptosis or promoting an immune-suppressive tumor microenvironment." (PMID 35873484, 2022). "Tumor growth may be inhibited by the pro-inflammatory milieu generated by effector cytokines such as TNF-α, which are released by CD8+ T cells." (PMID 36077620, 2022). "Moreover, CD103+ CD38+ CD8+ T cells were blocked by PD-1 in vitro and secreted higher levels of TNF-α to mediate anti-tumor immune response." (PMID 35906622, 2022). "Efficient pH-sensitive systems like chitosan respond to the subtle change of H+ ion concentration through proton attachment to the amino group (pKa ∼6.3) and subsequent swelling that brings about the liberation of encapsulated tumor necrosis factor-alpha (TNFa) in the tumor sites." (PMID 36284633, 2022). "TNF-α is originally discovered during 1975 that could kill mouse tumor cells, which is why we call it “tumor necrosis factor”." (PMID 36060429, 2022). "Increased expression of NF-kB and TNF-α promotes tumor initiation, progression, and angiogenesis." (PMID 35266425, 2022). "Immune cells can also directly influence the phenotype and function of tumor vessels through various cytokines, such as cytokines that inhibit tumor angiogenesis (interferon-α, interleukin-12, interleukin-18 or tumor necrosis factor) and chemokines (CXCL9, CXCL10 or CCL21)." (PMID 36569915, 2022). "TNF-α, produced mainly by activated macrophages, plays different roles in regulating multiple developmental and immune processes, such as killing and inhibiting tumor cells." (PMID 35585861, 2022). "Moreover, the expression of TNFα by tumor cells, leukocytes and stromal cells has led to production of inflammatory chemokines that recruited leukocytes with pro-metastatic effects." (PMID 35663982, 2022). "TNF-α is produced by tumor and inflammatory cells within the TME." (PMID 35493517, 2022). "However, the tumor-promoting and immunosuppressive activity of FAP+ fibroblasts have been demonstrated to suppress TNF signaling, thereby contributing to cancer–stroma–cancer interaction loop that promotes tumor progression." (PMID 36263225, 2022). "Several studies have documented the use of tumor-targeting Salmonella to deliver agents that induce apoptosis through a death receptor pathway, such as Fas Ligand, TNF-α, and TRAIL (Tumor Necrosis Factor-Related Apoptosis-Inducing Ligand) in the treatment of solid tumors." (PMID 36077761, 2022). "In fact, IL-1beta and TNF-alpha are significant stimulating factors in tumor cell adhesion in vitro and may therefore affect tumor recurrence to the peritoneum in vivo." (PMID 36171821, 2022). "TNF–TNFRSF1B signaling plays a central role in the negative regulation of M2 tumor-associated macrophages." (PMID 36230879, 2022). "Tumor‐infiltrating CD45RA−CCR7−Tregs were induced by tumor‐derived TNF‐α and could inhibit the secretion of IFN‐γ and proliferation of effector CD8+ T cells." (PMID 35474948, 2022). "Additionally, NK cell activation leads to the release of large amounts of IFNγ, TNF, and chemokines that exert strong anti-tumor functions and recruit immune cells into the tumor." (PMID 36372017, 2022).
tumor (continued). "In addition, regarding ADP@SWNT/TNFα+laser irradiation, the killing effect was greater, showing severe structural damage to the tumor and cell necrosis." (PMID 34994069, 2022). "However, due to this compatibility, they exert fewer anti-tumor effects against autologous tumors, having reduced cytotoxic capabilities due to lower CD107a degranulation, TNF-a, and IFN-g production." (PMID 36231109, 2022). "Moreover, TNF signaling plays important roles in regulating the biological roles of MDSCs, Treg cells, and some other immune cells, which affects the survival of tumor cells." (PMID 36358977, 2022). "Next, we asked if inactivation of STUB1 could sensitize human tumour cells to growth inhibition induced by the cytokines such as IFNγ and TNFα." (PMID 35982220, 2022). "In addition, VEGF 44, ICAM-1 45-47, TGF-β 48, IL-2, IL-649-51, and TNF-α 52 play an important role in the growth and metastasis of tumor cells, and can affect the expression of co-inhibitory molecules on immune cells." (PMID 36118529, 2022). "Tumor-infiltrating γδT17 cells are the main IL-17-producing cells in human colorectal cancer, and activated γδT17 cells promote the proliferation of PMN-MDSCs by secreting cytokines such as IL-17, IL-8, TNF-α and GM-CSF, and maintain its immunosuppressive activity, promoting tumor progression." (PMID 36685942, 2022). "Moreover, these Vγ2Vδ2 T cells activated jointly by Vγ2 x PD-L1 and PD-L1 tumor cells displayed multifunctional effector phenotypes, which co-expressed IFNγ, TNFα, and CD107a." (PMID 35784353, 2022). "PBMC co-cultured with tumor cells produced high amount of IL-6 and TNF-α than PBMC alone." (PMID 35444660, 2022). "To determine whether TNF is involved in TNFR1-regulated tumor development, we used TNF siRNA to silence TNF in KALLU+ cells." (PMID 36270982, 2022). "We also found that TNF signaling molecules secreted by monocytes/TAMs could play an important role in mediating tumor cell metastasis." (PMID 36291687, 2022). "CAR-T cells can kill tumor cells with specific target antigens through active cell lysis and the production of cytokines, including IL-1α, IL-2, IL-6, IL-8, IL-10, and tumor necrosis factor-α (TNF-α)." (PMID 36353643, 2022). "In addition, autophagy protects tumours from T cell-mediated cytotoxicity by inhibiting TNFα-induced apoptosis." (PMID 35183115, 2022). "The TNFα level was lower than it was during the earlier stages of tumor formation." (PMID 35933373, 2022). "In addition, KRT17 can activate different macrophage populations and subtypes (such as M1 and M2) through interferon γ, tumor necrosis factor-α and interleukin 10, which play an important role in tumor proliferation and differentiation." (PMID 35646078, 2022). "TNFRSF1A and TNFRSF1B, as the TNF receptors, were highly expressed in epithelial-like and mesenchymal-like malignant cells, suggesting that the TNF signaling pathway may promote tumor metastasis by inducing the EMT process of tumor cells." (PMID 36291687, 2022). "The results further demonstrated that the NIR‐triggered photothermal effect of ADP@SWNT/TNFα could effectively damage tumor cells, showing promise for its application in tumor therapy." (PMID 34994069, 2022). "In the context of a potential TNF function in cancer immunity, this discovery offered a first insight into the possible mechanisms that allowed this cytokine to go beyond inflammation and have a role in tumor immunity." (PMID 36358688, 2022). "Luteolin may function as a possible chemopreventive agent due to its capacity to change TNF-α from a tumor promoter to a tumor suppressor due to its ability to block NF-κB." (PMID 36556376, 2022). "In addition, TIGIT also directly induces exhaustion of tumor-infiltrating NK cells with lower expression of IFNγ and TNF or indirectly contributes to exhaustion of CD8+ T cells, impairing anti-tumor immune response." (PMID 36605439, 2022).
tumor (continued). "Moreover, the interaction between calreticulin and toll-like receptor 4 (TLR4) expressed on tumor cell surface promotes the secretion of TNFα and CCL19, which facilitates the migration and maturation of DCs, to limit the tumor progression in vivo." (PMID 36703971, 2022). "The Ulva polysaccharide can significantly increase the relative spleen and thymus weight of tumor-bearing animals, promote the secretion of tumor necrosis factor alpha (TNF-α), stimulate lymphocyte proliferation, and augment phagocytosis and secretion of NO and TNF-α in peritoneal macrophages." (PMID 35323501, 2022). "Moreover, we demonstrated that ERY974-induced cytokines, such as IFNγ and TNFα secreted from T cells activated by ERY974 induced TP expression in tumours." (PMID 36071036, 2022). "In addition, we measured the cytokines IL-1, IL-10, and TNF-α produced by the tumor-conditioned macrophage media." (PMID 36686704, 2022). "Specifically, multiple signaling pathways may be activated in the tumor microenvironment of subtype A, including TNF, SPP1, MIF, ANGPL, and ANGPTL." (PMID 36199581, 2022). "Furthermore, the effects of long-term Mito-Fu intake on the levels of TNF-α, pAMPK, FoxO1, and other genes or proteins prompted us to investigate its effects on typical tumor-related pathways." (PMID 35865479, 2022). "In addition, NF-kB and STAT3 are also common factors in tumor severity, and in the process of inflammation discovery, TNF-α and IL-1 were found to promote the pro-inflammatory phenotype of endothelial cells and fibroblasts by activating the NF-kB pathway." (PMID 36686745, 2022). "Moreover, Artemisia argyi polysaccharides (FAAP-02) were reported to improve anti-tumor activity by promoting the production of lymphocyte, TNF-α, IL-2, IL-4, IL-6, and IL-12." (PMID 35295918, 2022). "Furthermore, activated CD4+ helper and CD8+ cytotoxic lymphocytes (CTLs) stimulate type 1 immunity, which leads to anti-tumour activity by secreting tumour necrosis factor (TNF)- α, interferon (IFN)- γ, and other cytotoxins." (PMID 35804943, 2022). "Although TNF-α is a proinflammatory cytokine involved in chronic inflammation in RA and the development and progression of cancer, it also plays an essential role in combating infection and killing tumor cells through natural killer cells and CD8 lymphocytes." (PMID 35945635, 2022). "Free radical scavenging activities of CUR, as well as a decrease in the expression of inflammatory cytokines IL-1b, IL-6, and TNF- α, result in decreased cancer growth and down-regulation of enzymes such as protein kinase C, which regulate inflammation and tumor cell proliferation." (PMID 35159669, 2022). "Our research results confirm higher levels of TNFα in tumor tissue." (PMID 35208526, 2022). "MCs could provide the exact solution to TNF-α systemic toxicity by selectively releasing it, controlled only by tumor cell engagement, in and around the tumor cells." (PMID 35574362, 2022). "Immune-stimulating genes which have been virally introduced to GBM tumor cells are interleukins (IL), immune checkpoint inhibitors, immune stimulators, tumor necrosis factor (TNF)-related apoptosis-inducing ligand (TRAIL), E-cadherin, FMS-like tyrosine kinase 3 ligand (Flt3L), and tumor suppressors." (PMID 35954362, 2022). "The pro-inflammatory cytokines (such as tumor necrosis factor-α, interleukin-6, and interleukin-1β) from visceral adipose tissue contribute to a chronic inflammatory state in the whole body, thus creating a general environment better suitable for tumor growth." (PMID 36245841, 2022).
tumor (continued). "This signaling pathway dampens T cell receptor (TCR) signaling and CD28 signaling for T cell activation and the secretion of inflammatory cytokines, such as interferon-γ (IFN-γ), tumor necrosis factor (TNF), and interleukin-2 (IL-2), suppressing the cytotoxic effect on tumor cells." (PMID 36389700, 2022). "We, therefore, speculated that the Rnf31 knock-out sensitizes tumor cells to TNF-mediated apoptosis either indirectly, by abrogating NFκB pro-survival signaling, or directly, by facilitating caspase 8 cleavage." (PMID 35379808, 2022). "On the one hand, TNF can promote cancer as an endogenous tumor promoter." (PMID 35741587, 2022). "Also, the poor prognosis of cancer has been correlated with the upregulation of S100A4 in tumor cells, and its expression has been regulated by other factors like β-catenin, epidermal growth factor, tumor necrosis factor alpha (TNF-α), and methylation." (PMID 35965620, 2022). "Thus, we confirmed a direct link between the metabolic status of glucose and the efficacy and specificity of the tumor cell response to the tumorigenic effects of TNF-α, one of the major pro-inflammatory cytokines accompanying cancer growth." (PMID 36555705, 2022). "Similarly, tumor microenvironment-targeted TNF enhances CD8+ T-cell mediated anti-tumor immunotherapy." (PMID 36551505, 2022). "On the one hand, mast cells can release IL-4 and TNF-α to promote tumor cell apoptosis." (PMID 36611857, 2022). "The antitumorigenic immune components of tumor microenvironment are natural killer (NK) cells, dendritic cells (DC), cytotoxic T lymphocytes (CTLs), and M1 tumor-associated macrophages (M1 TAMS) secreting mainly proinflammatory cytokines like IL-1β, IL-1α, IL-6, IFNγ, TNFα etc.." (PMID 36496977, 2022). "Tumor infiltrating myeloid cells produce tumorigenic, pro-inflammatory cytokines (IL-6, IL-23, TNFα and IL-1) but, oddly enough, also anti-inflammatory cytokines (IL-10, TGFβ) as well as molecules with immune suppressive functions (Arginase1, VEGF, peroxinitrite and Indoleamine 2-3 dioxygenase)." (PMID 35237269, 2022). "For example, a conjugate consisting of TNF coupled to the tumor vasculature-homing peptide CRGRRST was shown to increase tumor vessel stability, vascular perfusion, and T-cell infiltration in a mouse model of pancreatic endocrine tumors, when administered biweekly at doses of 2 μg." (PMID 35890309, 2022). "To deeply investigate irAEs after aPD-L1 treatment in 4T1 tumor-bearing mice, we detected the infiltrated immune cells (T cells and macrophages) and the inflammatory cytokines (TNF-α, IFN-γ, and IL-6) in major organs (including heart, liver, lung, and kidney) after 2 days post-injection." (PMID 35710545, 2022). "Finally, upon exposure to a combination of IFNγ and TNFα, loss of STUB1 further sensitized tumour cells to growth inhibition in vitro." (PMID 35982220, 2022). "TNF-α have been reported to up-regulate the level of PD-L1 on the surface of tumor cells." (PMID 35705974, 2022). "Research has revealed that TNF-α induces diverse oncogenic and tumor-suppressive effects in TME and that dynamic changes in TME could influence the pharmacological action of PD-1/PD ligand 1 (PD-L1) blockers, potentially developing immunotherapy tolerance." (PMID 36505472, 2022). "Numerous studies have modified MSCs to overexpress cytokines that potentiate immune responses against cancer, such as interleukin (IL)-12, C-X-C Motif Chemokine Ligand 10 (CXCL10), IFN-β or tumor necrosis factor alpha (TNFα), thus reducing tumor growth and improving survival." (PMID 35631698, 2022). "In addition to SDF-1, fibroblast-derived IL-1β/IL-6, tumor cell-derived-IL-8, and tumor-infiltrated lymphocyte-derived-TNF-α were upregulated in OSCC patients with high TNM stage." (PMID 36045118, 2022).